NDST1 (N-deacetylase and N-sulfotransferase 1)
Description:
[Isoform 1]: Essential bifunctional enzyme that catalyzes both the N-deacetylation and the N-sulfation of glucosamine (GlcNAc) of the glycosaminoglycan in heparan sulfate. Modifies the GlcNAc-GlcA disaccharide repeating sugar backbone to make N-sulfated heparosan, a prerequisite substrate for later modifications in heparin biosynthesis. Plays a role in determining the extent and pattern of sulfation of heparan sulfate. Participates in biosynthesis of heparan sulfate that can ultimately serve as L-selectin ligands, thereby playing a role in inflammatory response (By similarity). Required for the exosomal release of SDCBP, CD63 and syndecan. [Isoform 3]: Lacks both N-deacetylase and N-sulfotransferase activities. Acts as a dominant negative on isoform 1, likely by changing the composition of enzyme complexes responsible for elongation and modification of heparan sulfates.
Synonyms: HSST; NST1; MRT46
Tractability: Small molecule: a structure with a bound ligand is known; it has a high-quality binding pocket. Antibody: UniProt predicts a signal peptide or a membrane-spanning region. PROTAC: its protein half-life has been measured.
Gene: Protein-coding gene on chromosome 5 (150,485,648 to 150,558,211, forward strand). Ensembl gene ENSG00000070614.
Subcellular location: Golgi apparatus, trans-Golgi network membrane (Isoform 1); Golgi apparatus, cis-Golgi network membrane; Golgi apparatus, cis-Golgi network membrane (Isoform 3)
Pathways (Reactome):
Metabolism: HS-GAG biosynthesis
Gene Ontology:
Molecular function: heparan sulfate N-deacetylase activity; heparan sulfate N-sulfotransferase activity; protein binding; deacetylase activity; N-acetylglucosamine deacetylase activity; hydrolase activity; sulfotransferase activity
Biological process: heparan sulfate proteoglycan biosynthetic process; heparin proteoglycan biosynthetic process
Cellular component: trans-Golgi network membrane; Golgi apparatus; Golgi membrane
Genetic constraint (gnomAD): Loss-of-function variants: 34 observed, 93.6 expected, observed/expected ratio (o/e) 0.36, 90% interval 0.28 to 0.48. The upper end of that interval is the gene's LOEUF score, 0.48, which puts it in group 2 of 6, group 1 being the genes least tolerant of losing a copy. Missense variants: 812 observed, 1,226.8 expected, observed/expected ratio (o/e) 0.66, 90% interval 0.62 to 0.7. Synonymous variants: 489 observed, 522.9 expected, observed/expected ratio (o/e) 0.94, 90% interval 0.87 to 1.01.
Homologues: Orthologues: chimpanzee NDST1 (99% identical), dog NDST1 (99% identical), rabbit NDST1 (98% identical), guinea pig NDST1 (98% identical), rat Ndst1 (98% identical), mouse Ndst1 (98% identical), pig NDST1 (96% identical), tropical clawed frog ndst1 (88% identical), zebrafish NDST1 (81% identical), zebrafish ndst1a (72% identical). Paralogues in human: NDST4 (71% identical), NDST2 (71% identical), NDST3 (70% identical), HS3ST3A1 (14% identical), HS3ST3B1 (14% identical), HS3ST4 (14% identical), HS3ST2 (13% identical), HS3ST6 (12% identical), HS3ST5 (11% identical), HS3ST1 (10% identical).
Diseases named in the same sentence as NDST1 in open-access papers:
NDST1 is named in the same sentence as 64 diseases in open-access papers, as found by Europe PMC text mining. Sharing a sentence is not in itself a finding about the gene and the disease. The quoted sentences say what the papers report.
breast carcinoma (7 papers, 2015 to 2024). "Hypermethylation of miR-149 downregulates its an expression and increase NDST1 expression, thereby leading to chemoresistance for breast cancer." (PMID 38748047, 2024). "For instance, NDST1, FRZB, ALAD, EDNRB, SSX2IP, and SFN have strong associations with breast cancer development, which bolsters our confidence in the viability of our model." (PMID 38007443, 2023). "Previous studies have demonstrated the tumorigenic effects of NDST1 in primary glioblastoma and breast cancer, suggesting that it is a promising target for anticancer therapy." (PMID 35935823, 2022). "With downregulated miRNA-149, the target gene GlcNAc N-deacetylase/N-sulfotransferase-1 (NDST1) was upexpressed; thus, the resistance of human breast cancer cells MCF-7 to ADM increased." (PMID 30744689, 2019). "In human breast cancer, HS agonist heparin increased NDST1 expression." (PMID 38748047, 2024). "In breast cancer, miR-149-5p was downregulated by the hyper-methylation of its promoter region and was found to be involved in Adriamycin-resistant breast cancer cells targeting GlcNAc N-deacetylase/N-sulfotransferase-1 (NDST1)." (PMID 28902136, 2017). "Interestingly, NDST1 is also related to chemoresistance in human breast cancer." (PMID 38748047, 2024). "A miR-191 dependent repression of protein level was shown for NDST1 in MGC803s, CDK6 and SATB1 in human epidermal keratinocytes, and CCND2, CSDA, and EGR1 in the human breast cancer cell line MDA-MB-231." (PMID 25992613, 2015).
lung carcinoma (4 papers, 2021 to 2024). "We recently demonstrated that antigen presenting cells carrying a CD11c driven mutation in the major cell-surface glycan sulfating enzyme Ndst1 are associated with augmented induction of anti-tumor CD8+ cytotoxic T cells relative to that of wildtype APCs in model lewis lung carcinoma tumors." (PMID 34715561, 2021). "Subsequent studies showed Ndst1 can also quench inflammatory responses in dendritic cells (DCs), with deletion of Ndst1 in DCs increasing antigen presentation and cytotoxic T cell responses in a lung carcinoma model." (PMID 39141086, 2024).
glioblastoma (3 papers, 2017 to 2022). The most malignant astrocytic tumor (WHO grade IV). "For example, the overexpression of miR-191 can enhance cell proliferation both in vivo and in vitro by negatively regulating the expression of NDST1 in human glioblastoma tissues and cells." (PMID 35966888, 2022).
hepatocellular carcinoma (3 papers, 2014 to 2019). A malignant tumor that arises from hepatocytes. "Sulfation of HS is not completely abolished in Ndst1f/fAlbCre+ hepatocytes; thus the impact of Ndst1 inactivation on Hamp expression in murine hepatocytes was incomplete, but comparable to the reduction in NDST1−/− human hepatoma cells." (PMID 31315930, 2019). "In multiple cases, miR-191 influences tumor progression by regulating proliferation; miR-191 promotes proliferation in hepatocellular carcinoma, and in gastric carcinoma by targeting NDST1, but inhibits proliferation in thyroid carcinoma by targeting CDK6." (PMID 25992613, 2015).
melanoma (2 papers, 2020 to 2022). A malignant, usually aggressive tumor composed of atypical, neoplastic melanocytes. "Metastatic melanoma has higher levels of EPAC1 expression than primary melanoma, and EPAC1 expression is linked to the expression of N-deacetylase/N-sulfotransferase-1 (NDST-1) and heparan sulfate (HS), which is a major part of the extracellular matrix." (PMID 35805104, 2022). "The HS2ST1 gene expression was similar between parental and stem-like melanoma cells, but NDST1 gene expression was elevated at stem-like melanoma cells comparing with parental melanoma cells." (PMID 33196458, 2020). "In melanoma A2058 cells, only the expression of NDST1 gene was detected (data not shown)." (PMID 33196458, 2020).
Obesity (2 papers, 2020 to 2025). Accumulation of substantial excess body fat. "To study the impact of changes in HS composition on obesity and T2D development we inactivated the sulfotransferase, Ndst1, in adipocytes (Ndst1flox/floxAdipoq-Cre+ [Ndst1 AKO]) and put the mice on a HFD." (PMID 41072794, 2025). "The combination of poor FGFR1-FGF1 signaling with obesity-induced insulin resistance results in worse lipolytic regulation in the adipose tissue of Ndst1 AKO mice and leads to the observed increased hepatic steatosis and hyperglycemia." (PMID 41072794, 2025). "Global knock-out of Ndst1 is perinatal lethal, but conditional knock-out mice allow investigating the impact of altered HS sulfation under various obesity- and inflammation-related conditions." (PMID 32508807, 2020).
periodontitis (2 papers, 2019 to 2024). An acute or chronic inflammatory process that affects the tissues that surround and support the teeth. "Of all investigated factors, the expression domains of Sdc1, HPSE1, EXT1, and NDST1 in gingival tissue displayed statistically significant differences between control and periodontitis group." (PMID 31611818, 2019). "The heparan sulphate biosynthesis enzymes (EXT1, EXT2, NDST1, and NDST2) displayed comparable correlation with the gingival tissue inflammatory infiltrate in the periodontitis group (EXT1, EXT2 and NDST1 correlated positively, and NDST correlated negatively)." (PMID 38674142, 2024). "Interestingly, HPSE1, EXTs, and NDSTs displayed similar correlation pattern in control and periodontitis group – positive correlations were found for EXT1, EXT2 and NDST1." (PMID 31611818, 2019). "However, the stromal expression domains of Sdc1 (p = 1,1033 × 10–6), HPSE1 (p = 0,0023), EXT1 (p = 1,2849 × 10–7), NDST1 (p = 0,000105), and CD45 (p = 0,003747) showed significant difference between controls and periodontitis group." (PMID 31611818, 2019). "However, the differential expression profiles of EXT1, NDST1 and HPSE1 do imply that certain perturbations in stromal HS content and composition might occur in periodontitis and might be responsible for dysregulation of inflammatory response." (PMID 31611818, 2019).
respiratory failure (2 papers, 2015 to 2022). The significant impairment of gas exchange within the lungs resulting in hypoxia, hypercarbia, or both, to the extent that organ tissue perfusion is severely compromised. "Mice deficient in NDST1 die shortly after birth, due to respiratory failure." (PMID 25767878, 2015). "Homozygous Ndst1−/− mutants die during the early postnatal development due to respiratory failure; heterozygous Ndst1+/− animals, however, are viable and do not display phenotypic changes in HS structure." (PMID 35216048, 2022).
cardioembolic stroke (1 paper, 2019). "Similar results were found for m6A-SNP rs2273235 in the NDST1 gene which was associated with cardioembolic stroke (P = 8.47 × 10−3)." (PMID 31156544, 2019).
chondrosarcoma (1 paper, 2017). A malignant cartilaginous matrix-producing mesenchymal neoplasm arising from the bone and soft tissue. "Treatment of H-HEMC-SS chondrosarcoma cells with 5-Aza-dc decreased NDST1 promoter methylation, increasing NDST1 mRNA expression, and reducing their proliferative and invasive properties." (PMID 28672878, 2017).
congenital diaphragmatic hernia (1 paper, 2024). A posterolateral defect of the diaphragm that allows passage of abdominal viscera into the thorax, leading to respiratory insufficiency and persistent pulmonary hypertension with high mortality. "Additionally, NDST1 is closely implicated in human disease, including Atherosclerosis, Holoprosencephaly, Congenital diaphragmatic hernia (CDH), Osteoarthritis (OA), allergic airway inflammation (AAI)." (PMID 38748047, 2024).
demyelination (1 paper, 2020). "Our data show that the majority of Ndst1+ cells at the margin of the LPC-induced lesion are mature CC1+ OLG revealing that mature OLG around a demyelination lesion, respond to post lesional cues." (PMID 32515730, 2020).
diabetics (1 paper, 2011). "In diabetics, there is a reduced level of the HSPG assembly enzyme N-deacetylase/N-sulfotransferase-1 (Ndst1) that is associated with decreased post-prandial clearance of triglyceride rich particles (TRPs) and hypertriglyceridemia." (PMID 21483695, 2011).
femoral neck fracture (1 paper, 2024). Fractures of the short, constricted portion of the thigh bone between the femur head and the trochanters. "The immunohistochemical expressions of SDC1, SDC2, SDC4, EXT1, EXT2, NDST1 and NDST2 in synovial intima and subintima were then analysed and compared with the control group (patients with femoral neck fracture)." (PMID 38674142, 2024).
Glucose intolerance (1 paper, 2025). Glucose intolerance (GI) can be defined as dysglycemia that comprises both prediabetes and diabetes. "Our results show that reduced HS sulfation and impaired HS production via Ndst1 and Ext1 inactivation in AT, respectively, promote glucose intolerance and insulin resistance by attenuating the endogenous FGF1-metabolic activity." (PMID 41072794, 2025). "Although no obvious morphological changes could be observed in adipose tissue of Ndst1 AKO mice after a weight loss intervention, their glucose intolerance remained unchanged, indicating that they also suffer from some form of metabolic inflexibility." (PMID 41072794, 2025).
Hepatic steatosis (1 paper, 2025). Steatosis is a term used to denote lipid accumulation within hepatocytes. "The increased hepatic steatosis in Ndst1 AKO mice is most likely a result of FFA spillover from adipose tissue." (PMID 41072794, 2025). "However, Ndst1 AKO mice presented with a marked increase in hepatic steatosis, as revealed by histological analyses." (PMID 41072794, 2025). "Livers from Ndst1 AKO mice had elevated triglyceride levels, suggesting advanced fatty liver disease." (PMID 41072794, 2025).
Insulin resistance (1 paper, 2025). Increased resistance towards insulin, that is, diminished effectiveness of insulin in reducing blood glucose levels. "In contrast, fasting glucose levels remained unchanged and insulin resistance remained prominent in Ndst1 AKO mice after 8 weeks on a low-fat chow diet." (PMID 41072794, 2025). "Using the HOMA-IR index as a measure of insulin resistance, the Ndst1 AKO mice showed a trend towards increased HOMA-IR even on a chow diet." (PMID 41072794, 2025). "Loss of liver Ndst1 did not affect weight gain, basal glucose levels, glucose tolerance, insulin resistance, or pyruvate tolerance, but did result in increased plasma triglyceride-rich lipoprotein levels compared to WT controls at 16-weeks of HFD feeding." (PMID 41072794, 2025). "Collectively, Ndst1 AKO mice show signs of increased hepatic inflammation, insulin resistance, and liver lipid accumulation in a DIO model." (PMID 41072794, 2025). "However, a trend towards decreased p-AKT was observed in the livers of Ndst1 AKO mice, suggesting increase liver insulin resistance." (PMID 41072794, 2025).
lymphatic disease (1 paper, 2010). "Further work is necessary to characterize alterations in lymphatic endothelial Ndst1 expression in human lymphatic disease." (PMID 21172016, 2010).
metastatic tumors (1 paper, 2018). "In metastatic tumors, NDST1 transcription levels were around 60% lower than controls in 75% of cases (p < 0.05), while in non-metastatic samples, the decrease was only around 40%, in 60% of the cases, though it was not statistically significant (p = 0.07)." (PMID 29940912, 2018). "The tissue distribution of NDST1 and NDST2 broadly overlap, and transcripts for both were detected in all samples analyzed in this study, with NDST2 appearing downregulated in all LSCRCs, while NDST1 transcription was downregulated in all metastatic tumors and in 60% of non-metastatic." (PMID 29940912, 2018).
Miscarriage (1 paper, 2026). A pregnancy that ends at a stage in which the fetus is incapable of surviving on its own, defined as the spontaneous loss of a fetus before the 22th week of pregnancy. "Multivariate logistic regression analysis by adjusting for all these variables (age, BMI, gestational days, RBC, WBC, Hb, smoking, and drinking) showed that the protein levels of MMP‐2, NDST1, and TSPAN4 were positively associated with miscarriage." (PMID 41168951, 2026).
multiple sclerosis (1 paper, 2020). A progressive autoimmune disorder affecting the central nervous system resulting in demyelination. "To examine the relevance of our findings for multiple sclerosis (MS) physiopathology, we examined Ndst1 expression in MS tissue." (PMID 32515730, 2020). "Comparison of healthy control, MS normal appearing WM and MS lesions showed that there is a significant increase of NDST1 staining in multiple sclerosis lesions vs. control (p=0.0014)." (PMID 32515730, 2020). "Furthermore, NDST1 expression in OLG was also increased in human postmortem tissues from multiple sclerosis patients." (PMID 32515730, 2020).
small cell lung carcinoma (1 paper, 2023). Small cell lung cancer (SCLC) is a highly aggressive malignant neoplasm, accounting for 10-15% of lung cancer cases, characterized byrapid growth, and early metastasis. "NDST1 participates in the synthesis of the heparan sulfate (HS) chain of HSPG, and a study found that it may provide an explanation for the clinical observation that heparin can improve outcomes in small-cell lung cancer (SCLC)." (PMID 37508851, 2023).
synovitis (1 paper, 2024). Inflammation of a synovial membrane. "Still, we concluded that syndecans (SDC1, SDC4), exostosins (EXT2) and sulfotransferases (NDST1) play a role in the progression and control of synovitis and, consequently, are potential therapeutic targets." (PMID 38674142, 2024). "Therefore, our data provide more information in support of syndecan (SDC1, SDC4), exostosin (EXT2) and sulfotransferase (NDST1) involvement in the progression and control of synovitis." (PMID 38674142, 2024). "SDC1, SDC4, NDST1 and EXT2 seem to be involved as inflammation moderators in low-grade OA synovitis and, therefore, should be further investigated as potential markers of disease progression and therapeutic goals." (PMID 38674142, 2024). "According to our study, the immunoexpression of SDC1, NDST1 and EXT2 is significantly increased in the intimal cells of OA synovial membrane in patients with lower histological synovitis scores and SDC4 in patients with higher synovitis scores, in comparison with non-OA controls." (PMID 38674142, 2024).
vasculitis (1 paper, 2018). "F137D had an increase in vasculitis score in Ndst1 deficient mice while E209I had a greater reduction in peritubular capillaritis in Ndst1−/− allografts." (PMID 30194334, 2018).
ZIKV infection (1 paper, 2025). "CRISPR/Cas9 screening indicated that NDST1 (N-deacetylase and N-sulfotransferase 1) and EXT1 might function as cell-dependent factors of ZIKV infection." (PMID 39927690, 2025).